MAFB (MAF bZIP transcription factor B)
Diseases named in the same sentence as MAFB in open-access papers (continued):
Sharing a sentence is not in itself a finding about the gene and the disease.
COVID-19 (continued). "Taken together, these data provide an additional support for the occurrence of an altered effective MAFB/MAF ratio in severe COVID-19 and chronic inflammatory disorders." (PMID 33312178, 2020). "The transcription factor MAFB is one of the three common gene targets of miR-223-3p and miR-24-3p and plays a noteworthy role in the immune system, acting as a critical checkpoint in macrophages and influencing COVID-19 severity." (PMID 39203974, 2024). "The transcriptional profile of prevailing macrophage subsets in severe COVID-19 led us to hypothesize that MAFB shapes the transcriptome of pulmonary macrophages driving severe COVID-19 pathogenesis." (PMID 37917179, 2023). "More importantly, MAFB knockdown led to a significant downregulation of the gene sets that define the pathogenic SPP1+ MØ (GSE145926), MoAM3 (GSE155249), or CD163+/LGMN+ MØ (accession number EGAS00001005634) subsets in severe COVID-19." (PMID 37917179, 2023). "Altogether, these results demonstrate that MAFB critically determines the transcriptome of SARS-CoV-2–exposed human macrophages and, particularly, the expression of genes that define profibrotic pathogenic pulmonary macrophages in severe COVID-19." (PMID 37917179, 2023). "Regarding the “HALLMARK_INFLAMMATORY_RESPONSE” gene set, MAFB and MAF were found to oppositely regulate the expression of a cluster of chemokine-encoding genes (CXCL10, CCL2, CCL7, CXCL9) that are associated to the COVID-19 “cytokine storm”." (PMID 33312178, 2020). "The altered MAFB/MAF expression ratio that we have found might have prognostic value in COVID-19 severity and progression, as well as potential therapeutic implications." (PMID 33312178, 2020). "This function as “rheostat” for type I IFN suggests that MAFB might contribute to the defective IFN production in COVID-19." (PMID 33312178, 2020). "On the prognosis issue, an immediate consequence of our hypothesis would be that the genes positively regulated by MAFB or negatively regulated by MAF could be prognostic biomarkers for severe COVID-19." (PMID 33312178, 2020). "Furthermore, MAFB knockdown drastically reduced the expression of the genes that are strongly upregulated (log2[FC] > 3.58, adjusted P [Padj] < 0.05) in postmortem lung tissue from patients with COVID-19 versus uninfected biopsy." (PMID 37917179, 2023). "Therefore, MAFB controls the expression of soluble factors that significantly contribute to COVID-19 pathogenesis (monocyte recruitment, fibrosis) and that constitute good predictors for COVID-19 severity and outcome." (PMID 37917179, 2023). "Next, analysis of the genes differentially regulated by MAFB and MAF on the disease-associated database DisGeNet using the clusterProfiler tool revealed a very significant enrichment of several terms related to respiratory deterioration (a firmly established symptom of COVID-19)." (PMID 33312178, 2020). "For example, individuals with moderate COVID-19 demonstrated lower levels of FOSL2, MAX, MAFB, IRF1, RUNX3, and HIF1A in CD14 and CD16 monocytes from other cohorts." (PMID 39712003, 2024). "Indeed, knock-down of MAFB prior to SARS-CoV-2 exposure significantly reduces the expression of chemokines that stimulate fibrosis (CXCL13, CCL18) and neutrophil recruitment (various CXCL chemokines), 2 processes that are closely linked to COVID-19 severity and post–COVID-19 pulmonary sequelae." (PMID 37917179, 2023). "For Mon IFI30, we also found MAFB and MAF as highly expressed and previous studies proposed their role for control of macrophage checkpoints in COVID-19 severity and as a marker for progression." (PMID 36230912, 2022). "Solid evidences are presented that link overexpression of MAFB and silencing of MAF expression with clinical and biological features of severe COVID-19." (PMID 33312178, 2020).
COVID-19 (continued). "Consequently, we hypothesize that MAFB and MAF shape the transcriptome of the fibrotic SPP1high and inflammatory monocyte-derived FCN1high pulmonary macrophage subsets, respectively, which exert a pathogenic role in severe COVID-19." (PMID 33312178, 2020). "MAF bZIP Transcription Factor B (MAFB), a gene highly upregulated in the temporal lobe of the male macaques, has been previously reported to play a sex-specific role in severe SARS-CoV-2 infectious disease (COVID-19)." (PMID 40427565, 2025). "Indeed, heightened levels of inactive GSK3 and MAFB-dependent proteins were observed in severe COVID-19 patients’ lung macrophages, highlighting the GSK3-MAFB axis as a therapeutic target for macrophage reprogramming." (PMID 40365863, 2025). "Based on these hallmarks, and considering the pivotal role of macrophages in COVID-19 pathogenesis, we hypothesize that the transcription factors MAFB and MAF critically contribute to COVID-19 progression by shaping the response of macrophages to SARS-CoV-2." (PMID 33312178, 2020). "Finally, since MAFB-dependent factors like IL-10, SPP1, CCL2, and CXCL13 are biomarkers for COVID-19 severity, we next assessed whether additional MAFB-dependent soluble factors might also predict COVID-19 severity or outcome." (PMID 37917179, 2023). "In the case of MAFB, its function as a “rheostat” for type I IFN production, and its ability to shape the transcriptome of pro-fibrotic SPP1high lung macrophages, suggest its participation in the defective type I IFN production and the pro-fibrotic response that characterize severe COVID-19." (PMID 33312178, 2020). "Therefore, considering the link between MAFB/MAF ratio and AHR expression, the proposed involvement of AhR in COVID-19 pathogenesis is well in agreement with our hypothesis on the contribution of MAFB and MAF to severe COVID-19." (PMID 33312178, 2020). "Indeed, reversing the macrophage MAFB/MAF expression ratio might impair the exacerbated inflammatory and profibrotic responses, and restore the defective IFN type I production, thus becoming a potential strategy to limit severity of COVID-19." (PMID 33312178, 2020). "Further supporting our hypothesis, additional GSEA also revealed co-enrichment of genes positively regulated by MAFB and negatively regulated by MAF in bronchoalveolar lavage fluid cells in COVID-19 patients (data not shown)." (PMID 33312178, 2020).
osteosarcoma (8 papers, 2022 to 2025). A usually aggressive malignant bone-forming mesenchymal neoplasm, predominantly affecting adolescents and young adults. "Detection of MAFB represents a promising prognostic biomarker that stratifies a subset of patients with the shortest overall survival in osteosarcoma and HCC." (PMID 36750911, 2023). "Of note, a recent study determined that MAFB is differentially expressed between tumor section and normal tissues in osteosarcoma, and MAFB transcriptionally regulated the portion of CSCs in osteosarcoma." (PMID 35333774, 2022). "Meanwhile, we provide a new function of KAT5 for the epigenetically inducing MAFB expression in the regulation of CSCs properties of osteosarcoma." (PMID 35333774, 2022). "In summary, we concluded that local anesthetic levobupivacaine inhibited stemness of osteosarcoma cells by epigenetically repressing MAFB though reducing KAT5 expression." (PMID 35333774, 2022). "KAT5 epigenetically enhanced MAFB expression in osteosarcoma cells." (PMID 35333774, 2022). "The expression of MAFB was decreased by KAT5 knockdown in osteosarcoma cells." (PMID 35333774, 2022). "MAFB contributes to tumorigenesis and stemness of osteosarcoma by targeting Sox9." (PMID 35333774, 2022). "The overexpression of KAT5 or MAFB could reverse levobupivacaine-attenuated cell proliferation and stemness of osteosarcoma cells." (PMID 35333774, 2022). "In addition, studies on osteosarcoma have reported that MAFB increases the expression of stem cell regulatory factor SOX9 at the transcriptional level." (PMID 36248367, 2022). "Therefore, we concluded that local anesthetic levobupivacaine inhibited stemness of osteosarcoma cells by epigenetically repressing MAFB though reducing KAT5 expression." (PMID 35333774, 2022). "Regarding mechanism, we identified that levobupivacaine inhibited MAFB and KAT5 expression in osteosarcoma cells." (PMID 35333774, 2022). "Our mechanical study showed that levobupivacaine inhibited MAFB and KAT5 expression in osteosarcoma cells." (PMID 35333774, 2022). "Moreover, we validated that the expression of MAFB and KAT5 was enhanced in clinical osteosarcoma tissues and the expression of MAFB was positively correlated with KAT5 in the tissues." (PMID 35333774, 2022).
viral infection (7 papers, 2018 to 2025). "However, if high MAFB protein levels were to be maintained, IFNβ1 transcription would not be sufficient resulting in an increased susceptibility to viral infection." (PMID 30567413, 2018). "During an acute phase of viral infection, MAFB expression reportedly decreases which allows for IRF3-mediated activation of IFNβ1 transcription enhancing a pro-inflammatory status." (PMID 30567413, 2018). "It has been hypothesized that MAFB may excessively suppress this pathway, potentially leading to a critical delay in the immune response during a viral infection." (PMID 40427565, 2025). "MAFB’s connection to COVID emerges when a heightened baseline suppression of IFN may lead to a critical delay in the immune response during a viral infection." (PMID 38045237, 2023). "Finally, dSpace analysis identified several genes (CCL2, OASL, CASP7, TMEM123, MAFB, VRK2, UBE2L6, NAPA) higher in patients with mild viral infection than those with severe viral infection or HCs." (PMID 33765435, 2021). "While the connection between TLR7, MAFB, and the IFN response offers an attractive possibility to explain the observed cytokine response, a model where increased MAFB expression because of increased engagement of TLR7 after viral infection raises several issues." (PMID 35065665, 2022).
colorectal cancer (6 papers, 2014 to 2023). A primary or metastatic malignant neoplasm that affects the colon or rectum. "For example, knockdown of MafB attenuated colorectal cancer cell proliferation via arresting the cell cycle at G0/G1 phase in vitro." (PMID 36750911, 2023). "In this study, we found that MAFB levels were increased in clinical colorectal cancer (CRC) samples, and higher expression correlated with more advanced TNM stage." (PMID 27829226, 2016). "Additionally, MAFB sumoylation has been proposed as a novel therapeutic target for colorectal cancer." (PMID 34277436, 2021). "MafB in CD14+ monocytes promoted tumorigenesis, cellular proliferation, and invasion in colorectal cancer, T cell acute lymphoblastic leukemia, nasopharyngeal carcinoma, and HCC." (PMID 31447817, 2019).
diabetic nephropathy (6 papers, 2019 to 2025). "MiR-320a was reported to induce diabetic nephropathy via inhibiting MafB." (PMID 38204237, 2024). "Besides, MAFB overexpression in podocytes is proved to prevent the progression of diabetic nephropathy." (PMID 39172054, 2024). "In addition, other research on diabetic nephropathy found that overexpression of MAFB in diabetic mice would decrease the level of the oxidative stress marker 8-hydroxydeoxyguanosine in urine." (PMID 35328083, 2022). "Our data indicated that miR-320a aggravated renal disfunction in DN by targeting MafB and downregulating Nephrin and Gpx3 in podocytes, which suggested that miR-320a could be a potential therapeutic target of diabetic nephropathy." (PMID 31102503, 2019). "In addition, recent studies have shown downregulation of MAFB in patients with FSGS, chronic kidney disease (CKD), and diabetic kidney disease." (PMID 41235225, 2025).
Duane retraction syndrome (6 papers, 2020 to 2025). Duane retraction syndrome (DRS) is a congenital form of strabismus characterized by horizontal eye movement limitation, globe retraction and palpebral fissure narrowing in attempted adduction. "One previous study in 2016 detected MAFB as the causative gene of Duane syndrome, which is characterized by abnormal eye abduction." (PMID 37895232, 2023). "For example, ADAM19 is known to participate in neuromuscular junction formation, while MAFB loss-of-function and dominant-negative mutations result in a congenital eye-movement disorder known as Duane retraction syndrome." (PMID 32380717, 2020). "Moreover, underexpression of MAFB was noted in patients with Focal Segmental Glomerulosclerosis (FSGS) with Duane Retraction Syndrome, who presented with MAFB variants, and its underexpression was associated with nephrological manifestations." (PMID 41235225, 2025). "In Duane syndrome, the cleaved MAFB protein may be encoded by the mutated MAFB gene." (PMID 37895232, 2023). "As proof of the importance of MAFB’s role, mutations in its leucine zipper domain also lead to FSGS with Duane retraction syndrome." (PMID 41235225, 2025). "Although most cases do not have an identifiable genetic cause, autosomal dominant variants in CHN1 or MAFB can cause isolated Duane syndrome, and variants in SALL4 cause Duane-radial ray syndrome (Duane syndrome plus abnormalities of forearm development)." (PMID 38500555, 2023). "Two mutations in the MAFB gene have been identified as causative in two different syndromic diseases where proteinuria is a feature, multicentric carpotarsal osteolysis and focal segmental glomerulosclerosis with Duane retraction syndrome (FSGS-DRS)." (PMID 32708597, 2020).
multicentric carpotarsal osteolysis syndrome (6 papers, 2016 to 2024). "MAFB Thr62Arg and several other amino acid exchanges at this position cause Multicentric Carpotarsal Osteolysis Syndrome (MCTO, OMIM #166300), and Thr62Arg in c-MAF results in the Ayme-Gripp syndrome (OMIM #601088)." (PMID 35406570, 2022). "Mutations in MAFB have been reported to be responsible for the multicentric carpotarsal osteolysis syndrome (MCTO)." (PMID 33806930, 2021). "MAFB has been associated with multicentric carpotarsal osteolysis syndrome (MTCO, MIM 166300)." (PMID 34122504, 2021). "In addition to orofacial clefting, mutations in MAFB cause multicentric carpotarsal osteolysis syndrome, which includes mild facial anomalies." (PMID 27560520, 2016).
nasopharyngeal carcinoma (6 papers, 2015 to 2023). A carcinoma arising from the nasopharyngeal epithelium. "MiR-223 negatively regulates the growth and migration of NPC cells via reducing MAFB expression, and this finding provides a novel insight into understanding miR-223 regulation mechanism in nasopharyngeal carcinoma tumorigenesis." (PMID 26055874, 2015). "In addition, miR-223 exerts a suppressive effect on nasopharyngeal carcinoma via targeting MafB and reducing MafB expression." (PMID 36750911, 2023).
Obesity (6 papers, 2015 to 2025). Accumulation of substantial excess body fat. "In this study, we investigated the mechanism by which hematopoietic‐specific MafB deficiency induces the development of obesity." (PMID 27419056, 2016). "Previous studies found that MafB expression is induced in proliferative β cells during pregnancy and in obesity, suggesting MafB may play a unique role in β-cell adaptation under certain metabolic stresses that demand more insulin production." (PMID 31208980, 2019). "Realizing that, on a C57BL/6J background, a deficiency of MafA alone was not sufficient to show the possible role of MafB in maintaining adult β-cell function, we implemented HFD treatment for mice to induce obesity and obtain a more severe phenotype." (PMID 31208980, 2019).
ischemic stroke (5 papers, 2015 to 2025). A stroke disorder caused by obstruction of blood flow to the brain, due to thrombotic (local blood clot formation) or embolic (due to a blood clot or other material traveling from another site) event. "We show that eCIRP causes microglial efferocytic dysfunction in ischemic stroke via TLR4/miR-155/MafB axis." (PMID 40766256, 2025). "Recent transcriptomic data also revealed that MafB is crucial for late-phase tissue repair function of monocyte-derived macrophages, including myelin phagocytosis, in ischemic stroke after attenuation of early-phase microglia." (PMID 40766256, 2025).
breast carcinoma (4 papers, 2014 to 2025). "Several of these genes have previously been associated with stem cell functions: MAFB and ZNF589 have been shown to be important in lineage-specific haematopoiesis, while HES4 is a down-stream target of the Notch signalling pathway which has been shown to affect breast cancer stem cell activity." (PMID 24583601, 2014).
focal segmental glomerulosclerosis (4 papers, 2020 to 2025). A renal disorder characterized by sclerotic lesions in the glomeruli. "These agonists have been shown to induce immunosuppression and fibrosis during focal segmental glomerulosclerosis (FSGS), and MAFB may be an important hub in these signals." (PMID 36012611, 2022).
type 2 diabetes (4 papers, 2015 to 2023). "It is also noteworthy that detrimental effects on adult β cell activity caused by MafA or MAFB reduction are much subtler than found for other islet-enriched TFs, many of which are associated with maturity-onset diabetes of the young." (PMID 37606041, 2023). "Since synthesis of non–β cell hormones appears to be negatively regulated by human MAFB and is associated with the loss of β cell identity and activity postnatally in type 2 diabetes (T2D), we examined here how MAFA and/or MAFB contributed to this process in adult mice and human islets." (PMID 37606041, 2023). "Some studies demonstrated that this miRNA protects against the progression of diseases such as cervical cancer by targeting phosphoinositide-dependent protein kinase 1 (PDK1) or type-2-diabetes by targeting the transcription factor MafB (Mafb)." (PMID 36142173, 2022). "Genome scans in families with type 2 diabetes identified a putative locus on chromosome 20q, MAFB was found with islet expressed sequence tags, and showed relatively high expression." (PMID 26204962, 2015). "Moreover, the decrease of MAFA, MAFB, and PDX1 expression levels have been found in human type 2 diabetes islet alpha and beta cells, which can be associated to islet cell dysfunction." (PMID 31405383, 2019).
autoimmune disease (3 papers, 2011 to 2025). A disorder resulting from loss of function or tissue destruction of an organ or multiple organs, arising from humoral or cellular immune responses of the individual to their own tissue constituents. "Among them, several studies on the regulation of type I interferon by MafB mention its role in autoimmune diseases such as psoriasis and viral persistence in patients with chronic hepatitis C." (PMID 40906796, 2025). "Here, the authors show that macrophage transcription factor MafB regulates total serum levels of C1q, which contributes to preventing autoimmune disease in mice." (PMID 29167450, 2017). "Furthermore, gene-targeting experiments demonstrated that MafB directly regulates the complement component C1q, leading to the prevention of systemic lupus erythematosus-like autoimmune diseases." (PMID 40906796, 2025).
hepatocellular carcinoma (3 papers, 2020 to 2025). A malignant tumor that arises from hepatocytes. "Enforced overexpression of MafB promotes hepatocellular carcinoma proliferation by enhancing cyclin D1." (PMID 36750911, 2023). "As H. hepaticus colonizes the intestine and the liver, the effect of H. hepaticus strain 3B1 (CCUG 44777) on MAFB gene expression was evaluated in vitro using intestinal HT-29 and hepatocellular carcinoma (HCC)-derived Huh7 and Hep3B cell lines." (PMID 32178359, 2020). "Moreover, cyclin D1, another important regulator of cell cycle progression, is identified as a direct target gene of MafB in hepatocellular carcinoma." (PMID 36750911, 2023).